TRPV4 (transient receptor potential cation channel subfamily V member 4)
Diseases named in the same sentence as TRPV4 in open-access papers (continued):
Sharing a sentence is not in itself a finding about the gene and the disease.
infection (14 papers, 2017 to 2025). The state of being infected such as from the introduction of a foreign agent such as serum, vaccine, antigenic substance or organism. "The calcium ion channel, TRPV4 is an essential mechanosensor that is required for effective phagocytosis in vitro and protects against infection-associated lung injury in vivo." (PMID 32676078, 2020). "Our laboratory is studying the role of TRPV4 in macrophage function during infection-associated lung injury." (PMID 28523001, 2017). "In regards to infection-associated inflammation, TRPV4 has been noted to be activated by heat which may provide a mechanism for immune cell activation in response to changes in body temperature." (PMID 34795674, 2021). "Thus, our findings suggest that TRPV4 regulates a feed-forward mechanism of phagocytosis in activated lung tissue macrophages when they interact with stiffened infection/injury-associated lung matrix." (PMID 28523001, 2017). "Collectively, TRPV4 is shown to play a novel role in protecting the lung from infection-associated lung injury by regulating the phagocytic and cytokine secretory response to infection, and therefore may be a potential therapeutic target in the pathogenesis of acute lung injury." (PMID 32676078, 2020). "We suspect that TRPV4 is recruited to the plasma membrane in response to PI3K activation to enhance itch sensation in the case of LPS infection." (PMID 38957035, 2024). "In macrophages, TRPV4 has been demonstrated to exert both protective and detrimental effects to the host tissue, by facilitating bacterial clearance in infection while promoting parenchymal injury in sterile inflammation." (PMID 36618411, 2022). "TRPV4 KO mice showed the worst course in the coinfection model, and all mice developed lethal infection within 7 days after the pneumococcal challenge." (PMID 34804016, 2021). "To evaluate the role of TRPV1 and TRPV4 on pneumococcal invasive diseases, we established a spontaneous pneumococcal lethal infection model after nasal colonization." (PMID 34804016, 2021). "Among TRPV4 KO mice, the number of PMNs was significantly lower in the coinfection model than in the mono-infection model (p = 0.018 by Mann–Whitney’s U test), which was the opposite result of an increase of PMNs in the coinfection model among wild-type mice." (PMID 34804016, 2021). "When coinfected with IAV, the production of TNF-α was greatly suppressed in TRPV4 KO mice compared with the mono-infection model." (PMID 34804016, 2021). "In macrophages, TRPV4 mediates formation of both reactive oxygen and nitrogen species, and regulates phagocytosis, thus facilitating bacterial clearance and resolution of infection." (PMID 32210976, 2020). "The data outlined in this review show the importance of macrophage TRPV4 in response to infection and lung injury." (PMID 32676078, 2020). "The role of TRPV4 in different macrophage populations after infection remains an important question." (PMID 32676078, 2020). "By inhibiting the activity of TRPV4 channels or knocking out TRPV4, it was hypothesized that the entry and replication process of the virus could be effectively prevented or slowed down, reducing the occurrence of infection." (PMID 39941149, 2025). "Moreover, MPTP-induced activation of the ER-resident chaperones GRP78 and GRP94 was inhibited by AAV-TRPV4 shRNAi infection, suggesting that knockdown of TRPV4 attenuated MPTP-induced ER stress." (PMID 35093118, 2022). "Interestingly, despite worse control of initial infection, TRPV4-/- mice had improved control of chronic infection at 150 days, as shown by reduced colony forming units compared to wild-type mice." (PMID 34795674, 2021). "Given the known interaction between TRPV4, integrins, and toll-like receptors (TLRs), it is worthy to mention the importance of epithelial/endothelial barrier function in the host response to infection." (PMID 34795674, 2021).
infection (continued). "As such, macrophage TRPV4 may exert both protective and detrimental effects to the host tissue, by facilitating bacterial clearance in infection while promoting parenchymal injury in sterile inflammation." (PMID 32210976, 2020). "In gram-negative infections with bacteria such as Escherichia coli and Pseudomonas aeruginosa, TRPV4 activation by ECM stiffening during infection synergizes with LPS-stimulated TLR4 activation of p38 and thereby promotes host defense and resolution from lung injury." (PMID 32210976, 2020). "In addition, TRPV4 activation can regulate the delivery of circulating immune cells to local sites of inflammation and infection by mediating vasodilation." (PMID 32210976, 2020). "M. tuberculosis can inhibit TRPV4 expression in macrophages, reducing intracellular Ca2+ resulting in dysfunctional delivery of mycobacteria to phago-lysosomal components and impaired acidification of phagosomes, which are necessary for effective infection control." (PMID 34795674, 2021). "Contrary to the mono-infection model, the level of TNF-α in the sera of TRPV4 KO mice was very low in the coinfection model." (PMID 34804016, 2021). "Similar time courses were observed, and around 70% of mice finally developed lethal infection among all groups in the mono-infection model (wild type; 65%, TRPV1 KO; 62%, TRPV4 KO; 75%, respectively)." (PMID 34804016, 2021). "In the mono-infection model, the levels of TNF-α were significantly higher in TRPV4 KO mice than those of wild type and TRPV1 KO mice (p < 0.05 and p < 0.001, respectively)." (PMID 34804016, 2021).
neurological disease (12 papers, 2016 to 2025). "This avenue of research warrants continued exploration to unravel the full therapeutic possibilities of TRPV4 modulation in mitigating neurological diseases linked to mitochondrial dysfunction." (PMID 39333347, 2025). "Further investigation into targeting TRPV4 for therapeutic interventions against neurological disorders associated with mitochondrial dysfunction holds potential for innovative treatments." (PMID 39333347, 2025). "Disruption of these contact points can impair mitochondrial function and induce cellular stress, implicating TRPV4 in the pathophysiology of neurological disorders." (PMID 39333347, 2025). "Recent studies have made significant progress in understanding the structure and functional role of TRPV4, shedding light on its involvement in pathological processes, particularly in the realm of neurological diseases." (PMID 39333347, 2025). "We delve into the structural and functional attributes of TRPV4, scrutinize its expression profile, and elucidate the possible mechanisms through which it participates in the pathogenesis of neurological disorders." (PMID 39333347, 2025). "Recent research has highlighted TRPV4-mediated mitochondrial dysfunction across various diseases, shedding light on potential mechanisms relevant to nervous system disorders." (PMID 39333347, 2025). "Here, we aim to provide a comprehensive exploration of the multifaceted contributions of TRPV4 to neurological diseases, spanning its intricate molecular mechanisms to its potential as a target for therapeutic interventions." (PMID 39333347, 2025). "The intention of this study was to build an evidence base to support the role of NKCC1 and TRPV4 as targets for managing CSF secretion before investigating their therapeutic potential for managing ICP in neurological disease and injury." (PMID 34573139, 2021). "Increasing evidence suggests that activation of TRPV4 is involved in the pathogenesis of some nervous system diseases and is responsible for neuronal injury." (PMID 27799895, 2016). "Since NMDA receptor channels and Cav2 channels play essential roles in synaptic transmission of the CNS, TRPV4 may be a better target for both the prevention and treatment of mTBI and related neurological disorders." (PMID 41024271, 2025). "As a multi-targeted therapeutic approach may prove necessary to treat these neurological disorders, other volume-regulating channels, such as TRPV4 channels and Kir4.1, need to be taken in account." (PMID 37443757, 2023). "In this study, we demonstrate that mutations within the TRPV4 ARD specifically disrupt interaction with a crucial regulator of the actin cytoskeleton, RhoA, providing a potential link between the function of TRPV4 in cytoskeletal dynamics and the pathogenesis of human neurological disease." (PMID 33664271, 2021). "Our study was conducted in rats in the absence of neurological disease or injury; therefore, we cannot dismiss the possibility that TRPV4 antagonism has different effects on CSF secretion under pathological conditions." (PMID 34573139, 2021). "We conclude that acute antagonism of either NKCC1 or TRPV4 is ineffective at reducing CSF secretion in rats absent of neurological disease or injury." (PMID 34573139, 2021). "We used a direct approach for measuring CSF secretion and found that antagonism of NKCC1 and TRPV4 did not decrease CSF secretion rates in healthy rats naïve to neurological disease or injury." (PMID 34573139, 2021).
respiratory diseases (10 papers, 2011 to 2024). "Understanding the druggability of TRPV4 channels and their ligands is essential for developing therapies in various medical fields such as oncology, cardiovascular diseases, and respiratory diseases." (PMID 39408877, 2024). "Nevertheless, TRPV4 channels are important pharmacological targets as new therapeutic option for respiratory disease." (PMID 33917551, 2021). "Collectively, TRPV4 is shown to play a novel role in modulating cytokine secretion and pulmonary inflammation and therefore may be involved in the pathogenesis of many respiratory diseases." (PMID 28523001, 2017). "Clinical expertise regarding TRPV4 antagonists is restricted to a sole agent, GSK2798745, tested in a small number of healthy volunteers or individuals suffering from cardiac and respiratory disorders." (PMID 38730655, 2024). "Taken together, these findings support a physical and functional interaction of TRPV4 and IP3R1 with NCXs as a novel TRPV4-mediated Ca2+ signaling mechanism and suggest a potential target for regulation of ASM tension and treatment of respiratory diseases, especially tracheal spasm." (PMID 31866874, 2019).
genetic disorders (5 papers, 2010 to 2025). "Mutation in TRPV4 gene results in some genetic disorders raising the medical and clinical interest of this thermoTRP channel." (PMID 25257900, 2014). "TRPV4 is mutated in several genetic diseases like skeletal dysplasia or neuromuscular diseases." (PMID 32186440, 2020). "In this context, it is worth mentioning that recent studies demonstrate that point mutations located at these ankyrin repeats at the N-terminus either increase or decrease the TRPV4 activity and results in genetic disorders." (PMID 20657843, 2010). "A preliminary screen on gain in invasion upon known or putative gain-of-function mutations, most identified in genetic diseases, was performed for TRPV4 (not shown), highlighting the importance of mutations in CaMBD." (PMID 32186440, 2020).
neurodegenerative disease (4 papers, 2016 to 2022). A disorder of the central nervous system characterized by gradual and progressive loss of neural tissue and neurologic function. "Our data highlight an integral role for CaMKII in neuronal TRPV4-associated Ca2+ responses, the importance of tightly regulated Ca2+ dynamics for mitochondrial axonal transport, and the therapeutic promise of TRPV4 antagonists for patients with TRPV4-related neurodegenerative diseases." (PMID 32471994, 2020).
neuromuscular disease (4 papers, 2011 to 2025). "The functional importance of these domains has been highlighted by the discovery of a cluster of neuromuscular disease-causing mutations on a cytosol-facing surface of the ARD in transient receptor potential vanilloid 4 (TRPV4)." (PMID 41338459, 2025). "Our experiments in transiently transfected MN-1 cells revealed that neuromuscular disease-causing mutations perturb the capacity of TRPV4 to immunoprecipitate with ARHGEF10." (PMID 41338459, 2025). "Analysis of cryo-EM structures of the TRPV4-RhoA complex have revealed that most TRPV4-ARD residues mutated in neuromuscular disease participate in RhoA binding." (PMID 41338459, 2025). "In transient receptor potential vanilloid 4 (TRPV4), the importance of this domain has been highlighted by the finding that gain-of-function neuromuscular disease-causing missense mutations cluster on the ARD surface." (PMID 41338459, 2025). "These two mutants were selected for study as they both cause multiple forms of TRPV4-mediated neuromuscular disease." (PMID 41338459, 2025). "Dominant mutations in ARHGEF10 are associated with forms of human neuromuscular disease, as well as a form of neuromuscular disease in dogs that involves vocal fold paresis, a characteristic feature of TRPV4-mediated disease." (PMID 41338459, 2025). "Mutations in ARHGEF10 have also been associated with a form of hereditary neuromuscular disease in Leonberger and Saint Bernard dogs that includes vocal fold paresis, a characteristic feature of TRPV4-mediated neuromuscular disease in human patients." (PMID 41338459, 2025). "One of the principal goals of this study was to gain insights into potential effects of neuromuscular disease-causing mutations on the TRPV4-ARD interactome." (PMID 41338459, 2025). "The observation that neuromuscular disease-causing mutations in TRPV4 cluster on a cytosol-facing surface of the ARD has further highlighted the functional importance of these domains." (PMID 41338459, 2025). "Comparison of the microarray interactomes of WT and mutant TRPV4-ARD identified 21 candidate binding partners exhibiting reduced interactions with neuromuscular disease-causing mutant forms of the ARD." (PMID 41338459, 2025). "In contrast, neuromuscular disease-causing mutations occur on the outer surface of the TRPV4 tetramer, suggesting that the pathogenic consequences of these mutations may result from altered interactions with ARD binding partners." (PMID 41338459, 2025). "Together, these results suggest that reduced interaction of neuromuscular disease-causing TRPV4 mutants with ARHGEF10 and the resulting loss of ARHGEF10-mediated inhibition may contribute to the increased ion channel activity characteristic of these mutant channels." (PMID 41338459, 2025). "The clinical features of SP-SMA, the most representative disease among the TRPV4-related neuromuscular diseases, are muscle weakness and motor dysfunction around the scapula and fibula." (PMID 39457418, 2024). "Together, these results suggest that RhoA serves as an auxiliary subunit for TRPV4, regulating TRPV4-mediated calcium homeostasis and disruption of TRPV4-RhoA interactions can lead to TRPV4-related neuromuscular disease." (PMID 37353484, 2023). "The ability of TRPV4 to bind to known ARD interactors calmodulin and ATP is not altered by neuromuscular disease-causing mutations, suggesting that the mutations do not substantially alter the fold or stability of the ARD." (PMID 41338459, 2025). "Little is known currently, however, about the extent of the TRPV4-ARD interactome, nor how it may be altered by neuromuscular disease-causing mutations." (PMID 41338459, 2025).
inflammation (3 papers, 2016 to 2024). Aberrant reaction of the microcirculation characterized by movement of fluid and leukocytes from the blood into extravascular tissues. "Importantly, this study also demonstrated that TRPV4 mediates D. farina-induced pulmonary inflammation and fibrosis through the activation of the TGF-β/PI3K/TRPV4/Rho pathway." (PMID 34831281, 2021).
musculoskeletal disorders (3 papers, 2016 to 2025). "Gain-of-function (GOF) mutations in the TRPV4 gene lead to a range of musculoskeletal disorders, while missense variations dominate the TRPV4 gene mutation spectrum." (PMID 40258774, 2025). "Several amino acid substitutions were identified in TRPV4 and related to musculoskeletal disorders." (PMID 32955611, 2021).
osteoarthropathy (3 papers, 2013 to 2023). "Fundamentally, ATP binding within the ankyrin repeat domain (ARD) of TRPV4 is the underlying mechanism to cause osteoarthropathy related diseases." (PMID 34198779, 2021). "A loss of function mutation in TRPV4 was shown to be associated with inherited osteoarthropathy, suggesting a role for TRPV4 in articular cartilage homeostasis." (PMID 23973152, 2013).
brain diseases (2 papers, 2020 to 2024). "In this review, I summarize the importance of TRPV4 activities in relation to brain temperature and focus on how hyperthermia-induced TRPV4 dysfunction exacerbates brain diseases." (PMID 39578735, 2024). "This interspecies difference from a gene expression point of view should be taken into consideration when modulators of TRPV2 or TRPV4 are investigated in rat models of brain disorders." (PMID 33262985, 2020).
movement disorder (2 papers, 2022 to 2025). Neurological conditions resulting in abnormal voluntary or involuntary movement, which may impact the speed, fluency, quality and ease of movement. "Similarly, TRPV4 expression is upregulated in the SN of MPTP‐induced PD mice, and overexpressing TRPV4 leads to movement disorders in mice." (PMID 41399206, 2025).
animal disease (1 paper, 2017). "In this regard, unraveling changes in TRPV4 channel expression and activity in cerebral arterial muscle pathologies of humans and animal disease models may lead to the development of TRPV4 channel targeted therapeutics to manage associated functional disorders of the cerebral circulation." (PMID 28472069, 2017).
cardiac diseases (1 paper, 2023). "In this context, it seems to be important to investigate the TRPV4 expression profile during life but also during the development of cardiac diseases." (PMID 37371124, 2023). "In this context, this review will discuss the latest findings on the pathophysiological role of the TRPV4 channel in the cardiovascular system and why an understanding of TRPV4 regulation may lead to novel therapeutical strategies related to cardiac diseases." (PMID 37371124, 2023).
central nervous system diseases (1 paper, 2023). "The top five predicted drugs that might upregulate MEG3 include RN-1734, a TRPV4 antagonist that was shown to reduce demyelination in central nervous system diseases as well as inhibit glial activation and IL-β and TNF-α production." (PMID 36869839, 2023).
mitochondrial disease (1 paper, 2025). "Our findings strongly suggest TRPV4 as a key molecular candidate to understand mitochondrial diseases." (PMID 39648544, 2025).
TRPV4 also shares sentences with these, for which no sentence is quoted: idiopathic pulmonary fibrosis (5 papers); Lung (4); retinopathy (4); bone disorder (3); gastrointestinal disorders (3); Intellectual disability (3); Parkinson disease (3); squamous cell carcinoma (3); acne (2); adenocarcinoma (2); bacterial infections (2); cerebral infarction (2); diabetic nephropathy (2); esophageal (2); intervertebral disc diseases (2); ischemic heart disease (2); Knee Osteoarthritis (2); pericarditis (2); periodontitis (2); renal cell carcinoma (2); scleroderma (2); sensorimotor neuropathies (2); spondylo-epimetaphyseal dysplasia (2); spondyloepiphyseal dysplasia (2); spondylometaphyseal dysplasia, Kozlowski type (2); achondrogenesis (1); acute cystitis (1); acute myocardial infarction (1); age-related macular degeneration (1); Age-related nuclear cataract (1).
A further 86 diseases each share a sentence with TRPV4 in 1 paper.